AKT1 (AKT serine/threonine kinase 1)
Diseases named in the same sentence as AKT1 in open-access papers (continued):
Sharing a sentence is not in itself a finding about the gene and the disease.
Proteus syndrome (continued). "Finally, activating somatic mutations in AKT1 cause Proteus syndrome (MIM 176920), a highly variable disorder of asymmetric overgrowth, tissue hyperplasia affecting multiple organs and increased tumour risk." (PMID 25972378, 2015). "One mechanism whereby PTN overexpression might result in macrodactyly was recently suggested by the discovery of an activating AKT1 mutation in Proteus syndrome." (PMID 22848377, 2012). "This implies that therapeutic agents for treating patients with Proteus syndrome would only need to reduce the effects of the exaggerated AKT1 signaling, which is in contrast to cytotoxic cancer treatments that are designed to kill the cells." (PMID 26657992, 2015). "Of note, in un-stimulated mutant cells, pAKT levels started to rise by 8 hours suggesting that it would be best to dose ARQ 092 frequently to maintain inhibition of AKT1 E17K in patients with Proteus syndrome." (PMID 26657992, 2015). "Proteus syndrome is a rare overgrowth syndrome (~ 200 reported cases worldwide) caused by a gain-of-function somatic mutation (c.49G > A, p.Glu17Lys) in the AKT serine/threonine kinase 1 (AKT1) gene." (PMID 40426219, 2025). "Proteus syndrome is defined as a score ≥ 10 points with an AKT1 pathogenic variant or a score of ≥ 15 points without the AKT1 variant." (PMID 33753828, 2021). "To evaluate a targeted therapeutic for Proteus syndrome, we used an in vitro model based on cells cultured from patients with Proteus syndrome, as there is no animal model for the AKT1 E17K mutation." (PMID 26657992, 2015). "Such a mechanism has been hypothesized for mutations in AKT1, which cause the Proteus syndrome, but have only been found in a mosaic state and never in all somatic cells." (PMID 26302956, 2015). "A notable example is ARQ092 (Miransertib), a selective allosteric inhibitor of AKT1, which has shown promise in clinical trials for patients with PI3K/Akt-driven tumors or Proteus syndrome." (PMID 39275052, 2024). "Our patient had no history of Proteus Syndrome or any other genetic disease, but AKT1 was found to be upregulated in his proliferating hemangioma." (PMID 35740845, 2022). "Of 53 individuals referred to our institution, 53 were diagnosed with Proteus syndrome and no individuals were diagnosed with AKT1-related overgrowth spectrum." (PMID 33753828, 2021). "We used both AKT1 E17K mutation-positive and mutation-negative SCC cells and fibroblast cultures with heterogeneous mutation levels, all derived from patients with Proteus syndrome." (PMID 26657992, 2015). "We found that VAFs of PIK3CA and AKT1 in affected tissues were around 20%, and no variant was identified in blood samples, further supporting previous findings which suggests that PIK3CA mutations are generally undetectable in the blood of patients with Proteus syndrome or with PROS, excluding MCAP." (PMID 33054853, 2020). "Except for AKT1, which was mentioned in the last ISSVA classification (strictly related to Proteus Syndrome), none of the mentioned genes were reported as having an impact on infantile hemangioma development or their therapy response." (PMID 35740845, 2022). "Excepting AKT1, which was mentioned in the last ISSVA classification (strictly related to Proteus Syndrome), none of the other genes were reported." (PMID 35740845, 2022).
Parkinson disease (49 papers, 2009 to 2026). A progressive degenerative disorder of the central nervous system characterized by loss of dopamine producing neurons in the substantia nigra and the presence of Lewy bodies in the substantia nigra and locus coeruleus. "Increased DJ-1 expression in patients with Parkinson’s disease promotes increased AKT1 protein phosphorylation." (PMID 35111368, 2022). "In Parkinson's disease (PD) model, circSV2b overexpression can reduce oxidative stress injury, protect dopaminergic neuron loss, maintain nigrostriatal function, and improve motor defects through miR‐5107‐5p‐FOXK1 (fork‐head box protein K1)‐AKT1 (serine/threonine protein kinase) signaling pathways." (PMID 37313330, 2023).
asthma (48 papers, 2014 to 2026). "Tests for pleiotropy and heterogeneity in the association between AKT1 and asthma yielded results greater than 0.05, reinforcing the robustness of these findings." (PMID 40420184, 2025). "MR analysis revealed a significant causal link between AKT1 and asthma, evidenced by an odds ratio (OR) of 1.097 with a 95% confidence interval (CI) of 1.019–1.181 and a P-value of 0.013." (PMID 40420184, 2025). "Similarly, Perilla seed decoction has been found to alleviate airway hyperreactivity in cough variant asthma model rats via the PI3K/AKT1/mTOR signaling pathway." (PMID 40264707, 2025). "AKT1 is an important factor in the PI3K-AKT signaling pathway, which plays a key role in many physiological processes such as cell growth and survival and is associated with airway inflammation and lung function changes in asthma (gianni, 2019)." (PMID 37274103, 2023). "Recent systems biology analyses identified four potential molecular triggers—AKT1, MAPK13, STAT1, and TLR4—as candidate regulators of asthma-associated signaling pathways." (PMID 40650018, 2025). "Gene and protein expression of the four potential asthma triggers, AKT1, MAPK13, STAT1, and TLR4, was analyzed in PBMC samples obtained from AA, NA, and HC." (PMID 40650018, 2025). "Here, we have analyzed theoretical signaling pathways related to four asthma trigger proteins, AKT1, MAPK13, STAT1, and TLR4, defined by previous systems biology study as proteins able to modify the activation of many effector proteins of respiratory diseases." (PMID 40650018, 2025). "Zisuzi Decoction ameliorates AHR and partially reverses airway remodeling through inhibition of PI3K/AKT1/mTOR, JAK2/STAT3, and HIF‐1α/NF‐κB signaling pathways, demonstrating effectiveness in cough‐variant asthma management." (PMID 41426510, 2025). "These components were subjected to molecular docking studies to evaluate their interaction with key asthma-related targets such as AKT1, TNF, and IL1B." (PMID 40420184, 2025). "PI3K/AKT1 signaling as calpain has been reported to modulate both PI3K and AKT1 in inflammation of lung tissues in different models of pulmonary artery and asthma." (PMID 35729674, 2022). "Finally, we obtained 7 predicted targets of baicalein for asthma treatment, namely AKT1, VEGFA, EGFR, SRC, MAPK3, MMP9, MAPK1." (PMID 38178132, 2024). "AKT1 promotes the airway myocyte hypertrophy and is observed to be activated in asthmatic subjects, which might lead to airway smooth muscle hyperplasia involved in asthma exacerbations." (PMID 35069542, 2021). "Our molecular docking confirmed interactions of these active components, particularly Kaempferol and Norephedrine, with core targets AKT1, TNF, and IL1B, underscoring their potential therapeutic roles in managing asthma." (PMID 40420184, 2025). "This regulation of cbl-b, EGFR, AKT1, and MAPK1 suggests new potential therapeutic targets for asthma treatment." (PMID 40264707, 2025). "In conclusion, this study supports the potential involvement of AKT1, MAPK13, STAT1, and TLR4 in asthma pathogenesis and highlights differences between allergic and nonallergic asthma at the molecular level." (PMID 40650018, 2025). "AKT1, downstream of PI3 K, can regulate various growth factors impacting lung function in asthma, modulate inflammatory cytokine IL6, and inhibit proliferation in human bronchial smooth muscle cells." (PMID 40420184, 2025). "In our study, we employed a network pharmacology approach to prioritize seven predicted targets (AKT1, VEGFA, EGFR, SRC, MAPK3, MMP9, MAPK1) of baicalein for asthma treatment, and confirmed its high binding affinity to these targets through molecular docking." (PMID 38178132, 2024). "For the molecular docking, the four target genes, AKT1, EGFR, VEGFA, and HSP90AB, were selected based on KEGG analysis results in the asthma pathway." (PMID 36836768, 2023).
asthma (continued). "Quercetin, luteolin, linolenic acid, adenosine, kaempferol, etc., were considered the potential core compounds, and PTGS2, ESR1, PTGS1, NOS2, AKT1, etc. were the main potential targets of BSYQ for asthma and IPF therapy." (PMID 35672815, 2022). "IL6, IL-1β, TNF, VEGFA, AKT1, etc., played an essential role in the PPI network, indicating the crucial roles in treating asthma and IPF." (PMID 35672815, 2022). "Furthermore, this study utilized network pharmacology to identify pivotal asthma treatment targets for YKS, including AKT1, TNF, IL1B, EGFR, IFNG, IL4, CASP3, and PTGS2." (PMID 40420184, 2025). "Mendelian randomization was employed to investigate causal relationships between asthma and core targets like AKT1, TNF, and IL1B, revealing a direct causality with AKT1 but not with TNF or IL1B, suggesting their indirect influence on asthma pathways." (PMID 40420184, 2025).
myocardial infarction (48 papers, 2013 to 2025). Gross necrosis of the myocardium, as a result of interruption of the blood supply to the area, as in coronary thrombosis. "In terms of individual siRNA treatment, administration of a FGFR1, PI3K p110, or Akt1 siRNA caused significant intensification of myocardial infarction." (PMID 24067542, 2013). "Exosomes obtained from LPS-pretreated BMSCs increased M2 macrophage polarization and attenuated post-myocardial infarction inflammation by inhibiting the LPS-dependent NF-κB signaling pathway and activating the AKT1/AKT2 signaling pathway." (PMID 36768406, 2023). "In this article, we summarized the mechanisms by which copper ions, microRNA, Akt1, inflammation, oxidative stress, mitochondria, and pericytes are involved in angiogenesis after myocardial infarction." (PMID 35600953, 2022). "In our previous studies, we utilized a unique and established stem cell engineered approach to deliver Wt and Akt-1−/− lin-c-kit+ stem cells following myocardial infarction." (PMID 23762381, 2013). "Our recent observations have shown that Akt-1 was activated in post-myocardial infarction following HDAC inhibition." (PMID 23762381, 2013). "This action caused phosphorylation of the signaling molecules PI3K p85, Akt1, and BAD, thereby reducing caspase 3 activity, cell death, and myocardial infarction in association with improvement of myocardial function." (PMID 24067542, 2013). "TSA also reduced active caspase-3 and stimulated Akt-1 in hearts with myocardial infarction, suggesting that these pathways could be involved in the increment in survival rate related to TSA." (PMID 39768722, 2024). "Recently using a myocardial infarction model, our observation exhibited that HDAC inhibition manifested an anti-hypertrophic effect, prevented cardiac modeling and improved myocardial functional recovery, which was associated with the activation of Akt-1 signaling." (PMID 23762381, 2013). "In contrast, VSMC specific deletion of Akt1 in mice demonstrates a milder phenotype without evidence of rupture or myocardial infarct, suggesting that the effects of Akt1 deletion are not solely mediated by VSMC expression." (PMID 28886156, 2017). "HDAC inhibition resulted in improvement in ventricular function and reduction of myocardial infarct, which was absent by the disruption of MKK3 and Akt-1." (PMID 23762381, 2013).
Stroke (48 papers, 2009 to 2026). Sudden impairment of blood flow to a part of the brain due to occlusion or rupture of an artery to the brain. "Existing studies have reported that AKT1 has therapeutic effects on stroke in terms of neuroprotection, promotion of neuronal regeneration and repair, anti-inflammatory effects, and vascular protection." (PMID 41011203, 2025). "Now, according to our DMDA approaches, with the filtering effect from the big data, we can settle this controversy at a high confidence level: the significance of AKT1 in the pathogenesis of stroke is undeniable." (PMID 40732222, 2025). "AKT1 is highly expressed in the nerve cytoplasm and is a key growth factor, inducing the survival of neurons affected by stroke." (PMID 36598916, 2023). "In addition, the Akt1/Nos3 signaling pathway is thought to be highly beneficial to stroke outcome, weather by upregulation of Akt1 or by subsequent activation of Nos3." (PMID 32558293, 2020). "The core targets of PPI are TNF,IL-6,ALB,AKT1,VEGFA, and CREB1, which play a key role in the regulation of stroke by DZSM." (PMID 34754318, 2021). "Accumulating evidence has confirmed that, under the injuries of stroke, cerebral ischemia, and I/R and activation of PI3K/Akt or PI3K/Akt/mTOR signaling pathway, PIK3CA, PIK3R1, AKT1, MAPK1, MAPK3 are main genes that play important roles in promoting cell survival and reducing cellular apoptosis." (PMID 35432563, 2022). "The core targets of DZSM for stroke are TNF, AKT1, VEGFA, and IL-1β, which are highly correlated." (PMID 34754318, 2021). "In hippocampal tissues, mRNA expression studies at 1 h and 24 h, and strongly elevated (Egr1, Akt1, Kras, Src, Foxo, Srf, Vegfr2, Nos3, Nos1) and decreased (Nos2, Nfkb) gene expression (Mapk1 not activated) also support BPC 157 beneficial effect on brain lesions, given in reperfusion in stroke-rats." (PMID 34203464, 2021).
oral squamous cell carcinoma (47 papers, 2015 to 2026). "The overexpression of AKT1 is linked to the development of oral squamous cell carcinoma (OSCC) and many other complex diseases." (PMID 35887580, 2022). "The upregulation of RAC-alpha serine/threonine-protein kinase (Akt1) and RAC-beta serine/threonine-protein kinase (Akt2) is the main cause of oral squamous cell carcinoma." (PMID 35251696, 2022). "Oral squamous cell carcinoma is characterized by the upregulation of RAC-alpha serine/threonine-protein kinase (Akt1) and RAC-beta serine/threonine-protein kinase (Akt2)." (PMID 35251696, 2022). "Oral squamous cell carcinoma is characterized by overexpression of Akt1 (RAC-alpha serine/threonine-protein kinase) and Akt2 (RAC-beta serine/threonine-protein kinase)." (PMID 34832886, 2021). "It was reported that Akt1 and Akt2 inhibitors can lead to oral squamous cell carcinoma treatment with no affinity toward monoamine oxidase B (MAOB)." (PMID 34832886, 2021). "In silico studies introduced LN as inhibitors of Akt1 and Akt2 with strong binding affinities of 11.5 kcal/mol and 11.1 kcal/mol, respectively, with no affinity toward MAOB, which can be an ideal candidate for oral squamous cell carcinoma treatment." (PMID 34832886, 2021).
cholangiocarcinoma (46 papers, 2013 to 2026). A carcinoma that arises from the intrahepatic biliary tree (intrahepatic cholangiocarcinoma) or from the junction, or adjacent to the junction, of the right and left hepatic ducts (hilar cholangiocarcinoma). "Results from KEGG pathway analysis indicated that the action mechanisms of YCHD for cholangiocarcinoma were implicated in hub targets of AKT1 and MAPK1." (PMID 33478536, 2021). "Downregulation of Akt1 has been associated with reduced proliferation in a variety of cancer cells including cholangiocarcinoma cells, suggesting an important role of Akt1 in cancer cell proliferation." (PMID 28008153, 2017). "RiskScore of cholangiocarcinoma patients with 10 genes calculated followed the formula: The RiskScore=0.429*VEGFC -0.434*NFKBIA-0.884*NLRX1+0.54*AKT1+0.629*CSRP1+0.406*EPO+0.833*IL31RA+1.023*LEP+0.341*MUC4+0.363*SEMA4B." (PMID 36817485, 2023). "Among all 10 prognostic specific immune-related genes, 4 genes (AKT1, EPO, MUC4, VEGFC) were considered as important predictors of relapse-free or overall survival and were implicated in immune microenvironment-related pathogenesis of cholangiocarcinoma." (PMID 36817485, 2023). "The vast majority of malignant tumors were in fact HCC, whereas cholangiocarcinomas (CCA) rarely occurred in SKP2/myr-AKT1 mice, in accordance to that described for myr-AKT1 mice." (PMID 25537506, 2015).
head and neck squamous cell carcinoma (46 papers, 2009 to 2025). A squamous cell carcinoma that arises from any of the following anatomic sites: lip and oral cavity, nasal cavity, paranasal sinuses, pharynx, larynx, and salivary glands. "We found that high expression of MMP1 and AKT1 is associated with lower survival chances in patients with head and neck squamous cell carcinoma compared to low expression." (PMID 38706907, 2024). "In the present study, we extend recent results showing that AKT1 restricts the invasive potential of breast tumor cells to head and neck squamous cell carcinoma (HNSCC) cells." (PMID 29506489, 2018). "A recent study in head and neck squamous cell carcinomas highlighted that genomic aberrations including EGFR amplifications, AKT1 amplifications and CSMD1 deletions, but not PIK3CA, were highly associated with responsiveness to PI3K-targeted drugs." (PMID 34404439, 2021).
heart failure (45 papers, 2012 to 2026). Inability of the heart to pump blood at an adequate rate to meet tissue metabolic requirements. "GSK-3β is a downstream target of Akt-1 and Akt-1 which via the phosphorylation of GSK-3β can promote the survival of chronically stressed cardiomyocytes in heart failure as demonstrated by previous works." (PMID 33564362, 2021). "Markers of heart failure were significantly reduced by mitochondrial AKT1 signaling." (PMID 37891673, 2023). "However, long-term activation of the AKT pathway, specifically AKT1, leads to cardiac failure characterized by decreased angiogenesis, increased pathological hypertrophy, and pathological left ventricular remodeling." (PMID 34945766, 2021).
diabetic nephropathy (44 papers, 2009 to 2026). "In addition to being directly related to T2DM, the polymorphisms of VEGFA, EGFR, PTGS2, and AKT1 genes are mainly related to diabetic vascular dysfunction and play an important role in diabetic vascular disease and diabetic nephropathy." (PMID 33134394, 2020). "The AKT1 signaling pathway plays a crucial role in safeguarding renal cells from apoptosis and preserving podocyte function in diabetic nephropathy." (PMID 40435181, 2025). "Sub-network from diabetic nephropathy datasets exhibits increased expression of AKT1 which gets accumulated in diabetic kidneys." (PMID 19997558, 2009). "Previous studies have reported that inhibition of activity of the Akt1 protein could decrease the deposition of fibronectin and improve diabetic nephropathy." (PMID 36438835, 2022). "Our findings also suggest a regulatory role of miRNAs in modulating target genes such as AKT1, MMP13, and IGF1R, implicating them in signaling pathways and cellular metabolism relevant to Diabetic Kidney Disease." (PMID 38891851, 2024). "A careful modular dissection and examination of networks from diabetic nephropathy datasets exhibit the interactions between EGFR with PTPN1 and CAV1 through AKT1 activation." (PMID 19997558, 2009).
Hyperinsulinemia (44 papers, 2012 to 2026). An increased concentration of insulin in the blood. "Mechanisms that have been implicated in driving diabetic cardiomyopathy include hyperinsulinemia, which acts to stimulate PI3Ka/Akt-1 pathways by which it mediates glucose uptake." (PMID 26215257, 2015). "The hyperinsulinemia was associated with hepatic insulin signaling protein dysregulation, as shown by the downregulation of IR-β, IRS-1, and Akt-1." (PMID 26718412, 2016).